MMP2 (matrix metallopeptidase 2)
Diseases named in the same sentence as MMP2 in open-access papers (continued):
Sharing a sentence is not in itself a finding about the gene and the disease.
gastric cancer (continued). "AQP3 serves a key role in the progression and metastasis of various types of cancer: AQP3 can upregulate matrix metalloproteinases (MMP1, MMP2 and MMP9) and induce EMT by activating the PI3K/AKT signaling in gastric cancer." (PMID 39611488, 2025). "In gastric cancer cells (AGS and NCI-N87), Tax inhibited colony formation and wound healing, leading to reduced MMP-2 and MMP-9 expression." (PMID 40563423, 2025). "USP19, which belongs to the category of potential pro-cancer factors, enhances the MMP2/MMP9 axis and related enzyme activities in patients with gastric cancer." (PMID 40280943, 2025). "We also found that PITX2 facilitated or repressed the lysosomal exocytosis of many SASP proteins, including MMP2, IGFBP2, and TIMP2, in senescent gastric cancer cells." (PMID 40995693, 2025). "The differences in the expression of hub genes, PTGS2, MMP9, MMP2, and CXCR4 genes were higher than normal gastric tissues in gastric cancer, and PPARG gene was lower than normal gastric tissues." (PMID 38457601, 2024). "Overexpression of TRIM25 in human gastric cancer cell lines (BGC823, SGC7901, and MGC803) reduced angiogenesis and MMP2 expression." (PMID 39768197, 2024). "For instance, the signaling pathway of integrin β1-mediated FAK/AKT leads to the expression of matrix metalloproteinase-2 (MMP-2) and MMP-9, which in turn boost the invasion, migration, and adhesion of gastric cancer cells." (PMID 38835077, 2024). "In gastric cancer, the downregulation of LOX expression can downregulate the expression of MMP-2 and MMP-9 in cancer cells." (PMID 39132501, 2024). "In gastric cancer cells, HMGB3 promotes cell invasion and migration by modulating MMP2 and MMP9 expression." (PMID 39684631, 2024). "After adding the MMP2 inhibitor to the coculture system, the EMT process of the low-expressing CDK5RAP3 gastric cancer group was restored." (PMID 35999359, 2023). "AQP3 overexpression increased MMP-3 secretion in prostate cancer cells and MT1-MMP, MMP-2, and MMP-9 in gastric cancer cells." (PMID 37681917, 2023). "Even more, in gastric cancer cell lines, AQP3 overexpression upregulated matrix metalloproteinases MT MMP1, MMP2, and MMP9, while its silencing decreased them via a PI3K/Akt-dependent manner." (PMID 37175840, 2023). "In gastric cancer, 6-shogaol intervention in gastric cancer BGC-823 cells significantly affects the expression of EMT related proteins and regulates E-cadherin protein, MMP-2, and MMP-9." (PMID 37875983, 2023). "Building on this, a study conducted in 2010 by Shen unveiled that B3GNT8 plays a role in regulating matrix metalloproteinase 2 (MMP-2) and tissue inhibitor of metalloproteinase 2 (TIMP-2) in gastric cancer cells." (PMID 38097951, 2023). "In gastric cancer, CEMIP was shown to alter the expression of MMP2, a known player in EMT progression." (PMID 35177031, 2022). "FPS reduced the tumor weight and blocked the expression of MMP-2 and MMP-14 in mice transplanted with gastric cancer, suggesting that FPS exerted anticancer effect by downregulating MMP-2 and MMP-14." (PMID 35662730, 2022). "Mechanistically, as an MMP2 targeting peptide, JP3 inhibits angiogenesis through TRIM25 (Tripartite motif containing 25)/SP1/MMP2 signaling, and plays a therapeutic role in gastric cancer." (PMID 36230577, 2022). "RGZ inhibits metastasis and migration, decreases MMP-2 expression, and prevents angiogenesis by blocking the vascular endothelial growth factor (VEGF) pathway in SGC-7901 gastric cancer cells." (PMID 36114448, 2022). "The delivery of miR-7 abolished the activity of NF-κB; expression of its transcriptional targets, namely ICAM-1, VCAM-1, vimentin, VEGF, MMP-2 and MMP-9; and mitigated gastric cancer metastasis in the lung and liver." (PMID 35163805, 2022). "In gastric cancer, FENDRR was found to increase cell migration and invasion via up-regulation of FN1, MMP2 and MMP9." (PMID 35183135, 2022).
gastric cancer (continued). "JWA alone and in combination with XRCC1, FAK, MMP2, MMD2 can predict the prognosis of gastric cancer patients." (PMID 36230577, 2022). "In terms of mechanism, WSP can inhibit the downstream EGFRVIII signaling pathway Akt-PI3K and further inhibit the secretion of cancer-related metastasis proteins such as MMP2 and MMP9, thus, significantly affecting the metastasis of gastric cancer cells." (PMID 36568183, 2022). "It was confirmed that the MMP-2 and VEGF were highly expressed in gastric cancer tissues and cells, and the overexpression of MMP-2 and VEGF was closely linked to the invasiveness and metastatic progress of cancer cells." (PMID 34976177, 2022). "R8-modified vinorelbine combined with schisandrin B liposomes can significantly inhibit gastric cancer metastasis by downregulating VEGF, VE-Cad, HIF-1a, PI3K, MMP-2, and FAK." (PMID 36339625, 2022). "Early studies have demonstrated an enhanced expression and activity of MMP-2 and MMP-9 in human gastric carcinoma in comparison to adjacent tissue and have suggested them as prognostic markers of a poor overall survival of patients." (PMID 35163805, 2022). "The RT-PCR data revealed an increased expression of MMP-13, which can be activated by MMP-2 and can activate MMP-9 in gastric carcinoma specimens, in comparison to normal control samples." (PMID 35163805, 2022). "When melatonin was used, the IL-1β/NF-κB/MMP-2/MMP-9 genes' expression and also invasion of gastric cancer cells reduced significantly." (PMID 34054953, 2021). "MMP-2 and MMP-9 are members of the MMPs family and have been reported to be overexpressed in gastric cancer." (PMID 33758617, 2021). "In conclusion, these results suggest that muscone exerts antitumor effects in vitro against the gastric cancer cell line SGC‐7901 via a pathway involving PI3K, AKT, c‐Myc, MMP‐2, and MMP‐9." (PMID 34531985, 2021). "After meta-analysis of GC gene expression profile chip, it was found that 7 of these genes, including AKR1B1, CTSK, MMP2, TLR4, ADRB2, PDE1C, and PTGER3, had significant differences in gastric cancer tissues." (PMID 34646828, 2021). "On the other hand, CAFs from scirrhous-type gastric cancer secretes exosomes CD81-negative/CD9-positive, which can promote cancer cell migration and invasion by activating the MMP2 signaling pathway." (PMID 33899109, 2021). "In the case of gastric cancer, a positive correlation between the concentration of the VEGF and MMP-2 and also VEGF and MMP-9 was found." (PMID 32594304, 2021). "For example, IL-32 induces Akt phosphorylation that activates β-catenin to promote IL-8, vascular endothelial growth factor (VEGF), matrix metalloproteinase 2 (MMP2) and MMP9 expression, which contribute to gastric cancer progression, and metastasis." (PMID 33406733, 2021). "Immunohistochemical studies indicate overexpression of MMP-2 and MMP-9 in 78% and 70% of all tested stomach cancer samples, respectively." (PMID 34770912, 2021). "Then, we investigated the correlation of TNC and VM with EMT markers in gastric cancer cells and found that TNC was positively correlated with N-cadherin, Vimentin, MMP2/9 and negatively related to E-cadherin, consistent with previous research." (PMID 34588421, 2021). "The regulation of MMP2 by CLDN6 and the role of both in cell migration and invasion are demonstrated in gastric cancer cells: CLDN6 increases the activity of MMP-2 to enhance cell migration and invasion by upregulating the expression CLDN1." (PMID 34948213, 2021). "To validate their relationship in gastric cancer cells, we used FAK inhibitor to block its function and the effects of Rab11a on cyclin D1, MMP2, and Bcl-2 were significantly reduced." (PMID 33178272, 2020). "Among MMPs, MMP-2 and MMP-9 belong to the gelatinases in matrix metalloproteinases, which are closely related to the invasion and metastasis of gastric cancer cells." (PMID 32256947, 2020).
gastric cancer (continued). "For gastric cancer, SOX9 was identified as a critical determinant in the control of epithelial-to-mesenchymal transition (EMT) and metastasis via affecting MMP-2 and MMP-9." (PMID 33076370, 2020). "The result demonstrated that PIN1 significantly promotes the expression of cyclin D1, MMP2, MMP9, β-catenin, and N-cadherin, while inhibits E-cadherin expression in gastric cancer." (PMID 32703934, 2020). "In gastric cancer cells, activated c‐Src can increase MMP‐2 and MMP‐9 expression and the degradation of the ECM, and play the role of VEGF‐C, thereby increasing the ability of gastric cancer cell metastasis through a series of processes." (PMID 31957271, 2020). "In gastric cancer, SNHG15 upregulation promotes cell proliferation and invasion by modulating the expression of MMP2/MMP9." (PMID 33243205, 2020). "Naringenin can significantly inhibit the growth of human gastric cancer cells (SGC-7901), reduce the expression of MMP-2 and MMP-9 in gastric cancer cells, and significantly suppress the proliferation, adhesion, invasion, and migration of SGC-7901." (PMID 33265939, 2020). "Previous studies have found that apatinib plays a role in the downregulation of MMP-2 and MMP-9 in gastric cancer." (PMID 32685465, 2020). "PRL-3 can up-regulate the expression of MMP-2 and MMP-9, which promote peritoneal metastasis of gastric cancer cells." (PMID 31546234, 2019). "In gastric cancer tissues with accompanying lymph node metastases, LOX and MMP-2 are positively correlated at the mRNA and protein level." (PMID 31777578, 2019). "A previous study has demonstrated that cannabinoid treatment result in the inhibition of gastric cancer cell invasion as well as the down-regulation of VEGF-A and MMP-2 expression mediated through the cannabinoid receptors CB1 and CB2." (PMID 29883990, 2019). "Studies have confirmed that in esophageal cancer and gastric cancer, MMP9 and MMP2 act as targets of NF-κB, which promote the invasion and metastasis of tumor cells." (PMID 31110076, 2019). "In order to understand gastric cancer further, we investigated the effects of LOX on MMP-2 and MMP-9 and its mechanisms in this disease." (PMID 31777578, 2019). "The frequency of haplotype CGC (MMP-2-1306C/T, TIMP-2 -418G/C and 303G/A) was apparently higher in patients with gastric cancer than the control group (P<0.05)." (PMID 31275061, 2019). "Previous studies indicated that the elevated expression of MMP2 and MMP9 correlated with the invasive capability of gastric cancer cells." (PMID 28994231, 2018). "Previous studies showed that MMP-2 and MMP-9 were overexpressed in gastric cancer, which accelerated the invasion of tumor cells in vitro and in vivo." (PMID 30150551, 2018). "As a candidate risk factor for gastric cancer, glucose-derived AGEs can promote gastric cancer cells invasion and metastasis via RAGE/ERK/Sp1/MMP2 pathway." (PMID 29262634, 2017). "MMP-2, MMP-7, and MMP-14 are members of matrix metalloproteinase family, which play an important role in gastric cancer invasion and migration." (PMID 29358963, 2017). "Histone deacetylation was involved in the down-regulation of FENDRR in gastric cancer cells and FENDRR overexpression suppressed invasion and migration by down-regulating FN1 and MMP2/MMP9 expression." (PMID 29069754, 2017). "ABG reduces cell motility, invasiveness, and activities of matrix metalloproteinase-2 (MMP-2) and MMP-9 in AGS human gastric cancer cells." (PMID 28587168, 2017). "Four hub genes with worse overall survival (OS) of gastric cancer patients were detected and the Kaplan Meier-plotter was applied to visualize them, including BGN, MMP2, COL1A1 and FN1." (PMID 29050278, 2017). "In fact, the expression of MMP2, 7, and 9 is significantly elevated in gastric cancer tissues, and the silencing of MMP3 expression in gastric cancer cells decreased GA invasiveness." (PMID 29285307, 2017).
gastric cancer (continued). "Recently, several studies have indicated that IL-32 induces the expression of MMP-2 and MMP-9 in gastric cancer and lung adenocarcinoma." (PMID 27589563, 2016). "FENDRR is down-regulated in gastric cancer, and decreased expression of FENDRR induces FN1 expression, which resulted in activation of MMP2/MMP9." (PMID 26238992, 2015). "In the current work, we found that TGR5 activation inhibited MMP2, MMP7 and MMP14 gene expression in gastric cancer cells." (PMID 26417930, 2015). "Subsequently, Xu and colleagues demonstrated that the knockdown of RAGE reduced GC cell proliferation and invasion of gastric cancer, decreased expression of AKT, PCNA and MMP-2, and induced cell apoptosis and cycle arrest." (PMID 25860956, 2015). "Subsequently, the increased FN1 expression contributes to the activation of MMP2/MMP9, leading to higher migration and invasion potential of gastric cancer cells, which was manifested by the greater number of metastatic nodules in the nude mice." (PMID 25167886, 2014). "Previously, it has been shown that AG490 markedly inhibits angiotensin II-induced STAT3 activation and the expression of MMP-2 and VEGF in gastric cancer cells." (PMID 24520293, 2014). "FENDER overexpression suppressed invasion and migration by gastric cancer cells in vitro, by downregulating FN1 and MMP2/MMP9 expression." (PMID 25167886, 2014). "In summary, our results indicate that elevated ADCY3 expression contributes to gastric cancer progression through the cAMP/PKA/CREB pathway, by increasing both mRNA expression and MMP2 and MMP9 activity." (PMID 24113161, 2013). "Based on our results, it is possible that via the upregulation of Cyclin D1, EGFR, Bcl-2, MMP-9 and MMP-2 expression and MVD, CXCR1/2 and their ligands are involved in mediating proliferation, growth, angiogenesis, invasion and metastasis of gastric carcinoma." (PMID 23420470, 2013). "Once H.Pylori has infected the stomach, it can stimulate the secretion of MMP-1, MMP-2, MMP-3 and TIMP-3 from gastric cancer cell, and finally prompt and speed up the progress invasion and metastasis of gastric cancer." (PMID 20637122, 2010). "Our unpublished data also proved that isoproterenol stimulated the expression of MMP-2 and MMP-9 in gastric cancer cells mainly through activating STAT3." (PMID 20939893, 2010). "In this study, real-time PCR was used to determine mRNA levels of MMP-2, MMP-7, MMP-9 and MT1-MMP in gastric cancers." (PMID 19586554, 2009). "Overexpression of MMPs has been observed in a series of cancers, with that of MMP-2, MMP-7, MMP-9 and MT1-MMP, in particular, typically present in gastric cancer." (PMID 19586554, 2009). "Second, some MMPs, such as MMP-2, MMP-7, MMP-9 and MT1-MMP, are frequenly overexpressed in gastric cancers, primarily in both tumor cells and stromal cells (except MMP-7, which is only expressed in tumor cells)." (PMID 19586554, 2009). "Real-time reverse-transcription PCR was performed to determine the mRNA expression of some members in MMP family, including MMP-2, MMP-7, MMP-9 and MT1-MMP in 32 gastric cancer specimens and corresponding matched normal tissue specimens." (PMID 19586554, 2009). "In a pioneer study, we showed 10 years ago that enhanced tissue levels of the matrix metalloproteinases (MMPs) MMP-2 and MMP-9 in gastric cancers, as determined by zymography, were related with worse overall survival of the patients." (PMID 16538217, 2006). "To corroborate these observations, we now assessed MMP-2 and MMP-9 with new techniques in an expanded group of gastric cancer patients (n=81) and included for comparison MMP-7, MMP-8 and the tissue inhibitors of MMPs, TIMP-1 and -2." (PMID 16538217, 2006). "We assessed the levels of MMP-2 (gelatinase A) and MMP-9 (gelatinase B) in 50 gastric carcinomas and corresponding mucosa using quantitative gelatin zymography." (PMID 8695357, 1996).
gastric cancer (continued). "Similarly, Nar (20, 40, and 80 μM) downregulated MMP-2 and MMP-9 expression in SGC-7901 gastric cancer cells, further supporting its metastasis-inhibitory potential." (PMID 40563423, 2025). "In gastric cancer, the roles of MMP2 and MMP9 have been described extensively in the literature compared to other MMPs, with both enzymes proposed as novel biomarkers for gastric cancer prognosis, indicating a major role in the gastric cancer metastatic process." (PMID 40906383, 2025). "Furthermore, a study using a xenograft model with transplanted gastric cancer tissue has revealed that chronic stress stimulates the β-adrenergic receptor (ADRB), which leads to the overexpression of VEGF, MMP-2, MMP-7, and MMP-9 in transplanted tumor tissue." (PMID 40362226, 2025). "Total saponins of panax can reduce the expression of Vemintin, SNAIL, MMP2 and MMP9 and increase the expression of P21, Caspase-3 and Bax in gastric cancer cell lines, thus promoting apoptosis of tumor cells and hindering their proliferation, migration and invasion." (PMID 38817861, 2024). "Previous studies have revealed that by downregulating MMP2 expression through the NF‐κB pathway, GKN1 inhibits metastasis in GC cells, suggesting that it may be a potential therapeutic target for gastric cancer." (PMID 39524138, 2024). "Similarly, sinulariolide, extracted from Sinularia flexibilis, has been shown to suppress MMP-2 and MMP-9 expression via the MAPK pathway in liver and gastric cancer cells, thereby diminishing cancer cell migration and invasion." (PMID 38374934, 2024). "In human gastric cancer cell lines, AQP3 induced expression of MT1-MMP, MMP2 and MMP9." (PMID 37681917, 2023). "Accordingly, we speculate that part of the potential mechanism by which CDK5RAP3 mediates gastric cancer cell migration, invasion and EMT is at least accomplished by regulating the expression of MMP2 in macrophages." (PMID 35999359, 2023). "The molecular mechanism of action of Les-4367 is associated with the induction of extrinsic and intrinsic apoptotic pathways, decreased MMP-2 and ICAM-1 concentrations—which are involved in the invasion of gastric cancer—as well as reduced levels of the pro-inflammatory cytokine IL-6." (PMID 37047765, 2023). "Furthermore, EP-CAM can regulate MMP2 and MMP9 in gastric cancer by activating the NFκB signaling pathway." (PMID 36107005, 2022). "Moreover, in the gastric cancer cell line SGC7901, tanshinone IIA down-regulated the expression of matrix metalloproteinase 2 (MMP-2), MMP-9, and FOXM1." (PMID 35897965, 2022). "In gastric cancer cell lines and tissues, ADCY3 overexpression promotes tumorigenesis by upregulating the expression of matrix metalloproteinase-2 (MMP2) and metalloproteinase-9 (MMP9) via the cAMP/PKA/CREB pathway, which increases cell migration, invasion, proliferation, and colony formation." (PMID 35832555, 2022). "MMP2 staining in the gastric cancer was scored on a scale of negative (−), weak (+), moderate (+ +), and strong (+ + +)." (PMID 35397606, 2022). "Similarly, in human gastric carcinoma cells, upregulated AQP3 levels correlated with increased MMP2 and MMP9 expression, whereas AQP3 silencing reduced MMP2 and MMP9 expression." (PMID 35163313, 2022). "Subsequently, we examined the mRNA and protein levels of phospho-ERK, MMP2/9 and markers of EMT and found that phpspho-ERK, MMP2/9 were significantly decreased and gastric cancer cells was induced to proceed mesenchymal-to-epithelial transition process upon TNC knockdown." (PMID 34588421, 2021). "The expression of the tissue remodeling marker (MMP2), the cell–cell interaction marker (β-catenin), and the cell–ECM interaction marker (integrin β1), which are involved in gastric cancer cell aggregation and are used to characterize the aggressiveness of cancer cells, were also investigated." (PMID 33816446, 2021).